CTLA4 (cytotoxic T-lymphocyte associated protein 4)
Diseases named in the same sentence as CTLA4 in open-access papers (continued):
Sharing a sentence is not in itself a finding about the gene and the disease.
osteoporosis (1 paper, 2025). A condition of reduced bone mass, with decreased cortical thickness and a decrease in the number and size of the trabeculae of cancellous bone (but normal chemical composition), resulting in increased fracture incidence. "Given that ICIs activate T cells, which, in turn, stimulate osteoclasts by increasing RANKL and cytokine levels, the risk of osteoporosis and fractures associated with ICIs is considered to occur uniformly, regardless of the target of action of the ICIs (i.e., PD-1, PD-L1, or CTLA-4)." (PMID 40143113, 2025).
ovarian serous cystadenocarcinoma (1 paper, 2020). A malignant serous cystic epithelial neoplasm arising from the ovary. "CTLA4 expression was also a prognostic factor for PFS in BLCA, CESC, CHOL, HNSC, KIRC, KIRP, ovarian serous cystadenocarcinoma (OV), THYM, and UCEC." (PMID 33072070, 2020).
palmoplantar pustulosis (1 paper, 2019). A rare skin disease characterized by chronic eruption of sterile pustules on an erythematous and desquamative background, affecting the palms and soles, sometimes also the lateral aspects of hands and feet. "Decreased expression of CTLA-4 has also been found in tonsillar T cells in patients with palmoplantar pustulosis." (PMID 31177287, 2019).
Paralysis (1 paper, 2025). Paralysis of voluntary muscles means loss of contraction due to interruption of one or more motor pathways from the brain to the muscle fibers. "The immune suppression or “immune paralysis,” driven in part by T-cell exhaustion and checkpoint pathway activation (PD-1/PD-L1, CTLA-4), undermines adaptive immune competence and predisposes survivors to secondary infection and late mortality." (PMID 41323595, 2025).
Parkinson disease (1 paper, 2017). A progressive degenerative disorder of the central nervous system characterized by loss of dopamine producing neurons in the substantia nigra and the presence of Lewy bodies in the substantia nigra and locus coeruleus. "Finally, the regulatory surface protein that limits T-cell activation signals, CTLA-4 (cytotoxic T-lymphocyte-associated protein 4), was decreased in Parkinson’s disease compared to HC in T cells (p = 0.029)." (PMID 28649611, 2017).
Pca (1 paper, 2021). "Despite the efficacy of immune checkpoint inhibitors such as ipilimumab (anti-CTLA-4) and nivolumab (anti-PD-1) in a variety of cancers including melanoma, lung, kidney and breast, clinical trials for these drugs in Pca have found them relatively inert or even toxic." (PMID 33800156, 2021). "Finally, ICB (both anti-CTLA4 and anti-PD1 antibodies) and MDSC-targeted therapy could then be utilized to break immunological tolerance and permit CD8+ cytolytic activity on PCa cells." (PMID 33800156, 2021).
pemphigus (1 paper, 2025). Pemphigus is a group of rare autoimmune diseases that cause blistering of the skin and mucous membranes (mouth, nose, throat, eyes, and genitals).This conditioncan occur at any age, but often strikes people in middle or older age. "Clinicians prescribing PD-1, PD-1L, or CTLA-4 inhibitors should be aware of the increased risk of pemphigus and monitor patients closely for early signs of this condition." (PMID 40034972, 2025).
pemphigus vulgaris (1 paper, 2023). Pemphigus is a group of chronic autoimmune skin diseases characterized by blister formations on the outer layer of the skin and the mucous membranes. "Emerging reports on the appearance of newly acquired pemphigus vulgaris or exacerbation of pre-existing pemphigus disease under both PD-1/PD-L1 and CTLA-4 inhibitors are also present in the literature." (PMID 37370736, 2023).
Penile Squamous Cell Carcinomas (1 paper, 2021). "The aim of this study was to investigate the expression of two of the most important targets of the ICI: PD-1/PD-L1 pathway and CTLA-4 in equine penile squamous cell carcinomas (epSCCs) to assess the feasibility of a future immunotherapeutic approach." (PMID 34359249, 2021).
pituitary carcinoma (1 paper, 2021). A primary or metastatic malignant neoplasm affecting the pituitary gland. "We report a patient with ACTH-secreting pituitary carcinoma, progressive after multiple lines of therapy including chemotherapy with TMZ, who demonstrated disease stabilization by a combination of ipilimumab (anti-CTLA-4) and nivolumab (anti-PD-1) ICI therapy." (PMID 33112279, 2021).
pituitary gland disorder (1 paper, 2022). A disease involving the pituitary gland. "Pituitary gland disorders are more frequent with anti CTLA-4 than with anti-PD1/PD-L1." (PMID 36713496, 2022).
pneumococcal infection (1 paper, 2012). Infections with bacteria of the species streptococcus pneumoniae. "The finding that CTLA-4 is highly expressed on a subset of T regulatory cells in resistant BALB/c, but not susceptible CBA/Ca mice following pneumococcal infection supports this assertion." (PMID 22563306, 2012).
pneumothorax (1 paper, 2024). Abnormal presence of air in the pleural cavity. "Furthermore, recent studies using PD-1, PD-L1, and CTLA-4 knockout mouse models have elucidated connections and mechanisms related to specific diseases, although no studies have yet linked these mechanisms to pneumothorax." (PMID 39459421, 2024).
primary biliary cholangitis (1 paper, 2017). Primary biliary cholangitis (PBC) is a chronic and slowly progressive cholestatic liver disease of autoimmune etiology characterized by injury of the intrahepatic bile ducts that may eventually lead to liver failure. "The connection between gene polymorphisms of cytotoxic T-lymphocyte-associated protein 4 (CTLA4) and primary biliary cholangitis (PBC) is still vague and blurred." (PMID 28642883, 2017).
primary progressive multiple sclerosis (1 paper, 2024). A multiple sclerosis that is characterized by steady worsening of neurologic functioning, without any distinct relapses or periods of remission. "The objective of this study was to investigate regulatory T cells (Tregs) and monocytes; specifically, the expression of CTLA-4 (CD152) and FOXP3+ in CD4+CD25+ Tregs and the expression of CD40+ and CD192+ monocyte subpopulations in subjects with primary progressive multiple sclerosis (PPMS)." (PMID 38398067, 2024).
psychological distress (1 paper, 2024). "This study examined associations between symptoms of maternal prenatal psychological distress and percentages of maternal circulating FoxP3+ Tregs and six Treg subpopulations expressing Helios, CD45RA, CTLA-4, PD-1, TIGIT, or TIM-3." (PMID 38016492, 2024).
Pv (1 paper, 2018). "As a result, all of these findings suggest that +49A>G and CT60A>G polymorphisms of the CTLA-4 gene may play a role in the pathogenesis of Pv." (PMID 29850619, 2018). "In the present study, −318C>T, +49A>G, and CT60 polymorphisms were studied to evaluate their contributions to the pathogenesis of Pv, focusing on their potential effects on the activity and function of the CTLA-4 molecule." (PMID 29850619, 2018). "Although our population size was relatively small, we believe that our results will contribute to meta-analysis studies which have aimed at understanding the role of CTLA-4 on the pathogenesis of Pv." (PMID 29850619, 2018). "Furthermore, decreased expression and/or broken binding with B7 in CTLA-4 may contribute to the pathogenesis of Pv by changing the T cell response." (PMID 29850619, 2018).
reactive arthritis (1 paper, 2023). Reactive arthritis (ReA) is an autoimmune disorder belonging to the group of seronegative spondyloarthropathies and is characterized by the classic triad of arthritis, urethritis and conjunctivitis. "At the same time, knee involvement and reactive-arthritis-like symptoms are more common when combined with anti-CTLA-4." (PMID 36981837, 2023).
rectal tumor (1 paper, 2024). "In our study, FOXP3(r = 0.179), CD72(r = 0.155), RUNX1(r = 0.327), LAG3(r = 0.194), CTLA4(r = 0.236) have a positive correlation with AP3M2 in Colon Neoplasm, but no irrelevancy in rectal tumor." (PMID 38177168, 2024).
Recurrent infections (1 paper, 2025). Increased susceptibility to infections as manifested by repeated bouts of infection. "Monoallelic germline mutations in the Cytotoxic T-lymphocyte antigen-4 (CTLA4) gene result in CTLA-4 deficiency (CTLA-4d), a complex IEI characterized by a broad and multifaceted clinical spectrum, including various autoimmune manifestations, lymphoproliferation, and recurrent infections." (PMID 41009791, 2025).
renal adenocarcinoma (1 paper, 2015). "Another study with vaccinia virus (VV) and CTLA4 inhibition in a syngeneic subcutaneous mouse renal adenocarcinoma model showed that if the combination of virus with anti-CTLA4 was administered on the same day (Day 0) the therapeutic effect of the addition of anti-CTLA4 was diminished." (PMID 26712782, 2015).
renal dysfunction (1 paper, 2022). "In our longitudinal prospective and case-control study, we examined in peripheral blood the role played by the FOXP3 and CTLA-4 transcripts as possible biomarkers of clinical outcomes, such as aTCMR, de novo DSA development and renal dysfunction." (PMID 35109826, 2022). "The purpose of our study was to develop a new non-invasive diagnostic tool, based on an accurate analysis of molecular FOXP3 and CTLA-4 mRNA expression pattern in peripheral blood, during the first post-transplant year, capable to predict aTCMR onset, de novo DSA development and renal dysfunction." (PMID 35109826, 2022).
retroperitoneal fibrosis (1 paper, 2023). "In clinical practice, IgG4-related retroperitoneal fibrosis can occur as an immune-related adverse event when administering anti-PD-1 and anti-CTLA-4 antibodies for cancer immunotherapy." (PMID 38098256, 2023).
salivary gland carcinoma (1 paper, 2020). A carcinoma that arises from the major or minor salivary glands. "These were the PD-1/PD-L1 interaction, that has already been evaluated in SDCs 16 and tested in advanced salivary gland carcinomas 14, as well as the CTLA-4/DC86 and TIM-3/galectin-9 interactions." (PMID 32292502, 2020).
salivary gland tumors (1 paper, 2024). "The distribution of T regulatory cells (Tregs), IL-17-producing lymphocytes, and CTLA4+ lymphocytes was analyzed in the plasma of patients with nineteen benign and eight malignant salivary gland tumors and compared to a control group." (PMID 39684268, 2024).
schizophrenia (1 paper, 2017). A major psychotic disorder characterized by abnormalities in the perception or expression of reality. "Single nucleotide polymorphisms have been analysed in many cytokines, in particular, those that are associated with altered levels in schizophrenia such as TNF-α, IL1-β, IL-6, IL-10, INF-γ, and in the genes encoding the immune system regulatory proteins CTLA-4 and CD28." (PMID 29317797, 2017).
scleroderma (1 paper, 2021). Scleroderma is a rare autoimmune connective tissue disorder characterized by abnormal hardening of the skin and, sometimes, other organs. "Despite 2 further cycles of combined anti-PD1 (nivolumab 1 mg/kg) and anti-CTLA4 (ipilimumab 3 mg/kg) immunotherapy 3 weeks apart, followed by 1.5 cycles of Fotemustine, the patient died 22 months after the development of the scleroderma-like skin changes." (PMID 33879687, 2021).
Seizure (1 paper, 2025). A seizure is an intermittent abnormality of nervous system physiology characterized by a transient occurrence of signs and/or symptoms due to abnormal excessive or synchronous neuronal activity in the brain. "Seizures in CTLA4 deficiency often result from encephalic inflammatory infiltration, although some reported cases presented with tonic–clonic seizures for which clinical and radiologic investigation could not identify an underlying cause." (PMID 41009791, 2025).
septic peritonitis (1 paper, 2024). Septic peritonitis is an inflammatory condition of the peritoneum that occurs secondary to microbial contamination. "Using a murine model of septic peritonitis in the context of chronic alcohol exposure, we investigated the T cell coinhibitory marker CTLA-4 and found an increase in its expression within the CD4+ T cell compartment." (PMID 38226924, 2024).
serous carcinoma (1 paper, 2025). "However, in a cohort of chemotherapy-naïve high-grade serous carcinoma patients, tumor-infiltrated T cells expressing PD-1, LAG-3, and CTLA-4 were linked to favorable relapse-free survival and OS, whereas TIM-3+ cells were associated with reduced OS." (PMID 41221283, 2025).
Shock (1 paper, 2017). The state in which profound and widespread reduction of effective tissue perfusion leads first to reversible, and then if prolonged, to irreversible cellular injury. "In line with previous reports, septic shock patients also showed high levels of CTLA4 expression when compared to healthy individuals." (PMID 28363639, 2017).
skin abscesses (1 paper, 2017). "Of the CTLA4 Ig treated mice, two developed skin abscesses by the end of the experiment, which were deemed to be unhealed." (PMID 28264025, 2017). "It is important to note that mice receiving CTLA4 Ig had significantly fewer open skin lesions compared with PBS controls due to greater skin abscess formation instead of skin necrosis." (PMID 28264025, 2017).
skin infection (1 paper, 2017). An inflammatory process affecting the skin, caused by bacteria, viruses, parasites, or fungi. "In this study, we demonstrated that both anti-TNF therapy and CTLA4 Ig treatment significantly decreased the severity of skin infection and caused smaller post-infectious hyperpigmentation compared with controls." (PMID 28264025, 2017). "The aim of this study was to examine the differential effects of anti-TNF versus CTLA4 Ig treatment on S. aureus skin infections in mice." (PMID 28264025, 2017). "Interestingly, both anti-TNF (p<0.001) and CTLA4 Ig (p<0.01) treatments significantly decreased the size of skin hyperpigmentation on day 18 after skin infections, strongly suggesting that both TNF-alpha and T-cell activation are responsible for post-inflammatory hyperpigmentation." (PMID 28264025, 2017). "In summary, our data suggest dual effects of CTLA4 Ig and anti-TNF therapies on S. aureus skin infection." (PMID 28264025, 2017). "Both CTLA4 Ig and anti-TNF treatment resulted in less severe skin infections and smaller post-infectious hyperpigmentation compared with controls." (PMID 28264025, 2017). "Neither kidney abscesses nor bacterial growth from kidney homogenates was found, suggesting that anti-TNF and CTLA4 Ig do not facilitate the systemic spread of bacteria from a local skin infection." (PMID 28264025, 2017). "Although a more clinically relevant model (skin infection by abrasion) was used in this study, it remains unclear whether anti-TNF treatment or CTLA4 Ig has any impact on S. aureus invasion through the skin barrier." (PMID 28264025, 2017). "Both CTLA4 Ig and anti-TNF therapies attenuate disease severity but may prolong the healing time required for S. aureus skin infections." (PMID 28264025, 2017). "Our data demonstrate that both anti-TNF and CTLA4 Ig treatment attenuate the severity of S. aureus skin infection without affecting host bacterial clearance." (PMID 28264025, 2017). "However, the effects of CTLA4 Ig and anti-TNF treatments on a local S. aureus infection (e.g., skin infection) might differ from their effects on a systemic infection." (PMID 28264025, 2017). "On the one hand, both CTLA4 Ig and anti-TNF therapies attenuate the severity of S. aureus skin infections and have no impact on bacterial clearance in skin tissues." (PMID 28264025, 2017).
small cell carcinoma (1 paper, 2018). A neuroendocrine carcinoma composed of small malignant cells which are often said to resemble "oat cells" under the microscope. "In small cell cancers of the lung, CheckMate 032 showed that nivolumab, a PD-1 inhibitor, with or without ipilimumab, a CTLA-4 inhibitor, provides durable responses for some patients who have failed one or more platinum-containing therapy." (PMID 29743117, 2018).
Staphylococcus aureus (S. aureus) infection (1 paper, 2017). "We recently demonstrated that both CTLA4 Ig and anti-TNF treatment aggravate systemic Staphylococcus aureus (S. aureus) infection in mice, but with distinct clinical manifestations." (PMID 28264025, 2017).
tongue cancer (1 paper, 2023). A malignant neoplasm affecting the tongue. "In a preclinical study using immunocompetent mouse model with tongue cancer treated by an inhibitor of CTLA-4, the authors compared efficacy between a local treatment of lymph nodes to no local treatment." (PMID 37539054, 2023).
tongue tumors (1 paper, 2019). "Moreover, we observed that mEER tongue tumors were relatively resistant to α-Lag3 monotherapy as compared to α-PD-1 or α-CTLA-4." (PMID 31533840, 2019). "In addition to the differential PD-1 expression in tongue- and flank-implanted mEER tumors, CD8+ T cells from tongue tumors showed higher levels of additional immune checkpoint inhibitory molecules, CTLA-4 and Lag3." (PMID 31533840, 2019). "Furthermore, we observed that supplementing α-PD-1 + α-CTLA-4 treatment with STING agonist administration into the flank tumors was associated with a decrease in the frequencies of CD4+Foxp3+ Treg as well as of MDSC expressing Arginase 1 in both flank and tongue tumors." (PMID 31533840, 2019). "Intratumoral STING activation along with a combination of α-CTLA-4 and α-PD-1, relative to no treatment or individual treatments, produced the most significant survival advantage in this pseudometastasic setting with regression of both flank and distant tongue tumors." (PMID 31533840, 2019).
toxic epidermal necrolysis (1 paper, 2023). Toxic epidermal necrolysis (TEN) is an acute and severe skin disease with clinical and histological features characterized by the destruction and detachment of the skin epithelium and mucous membranes. "True Stevens Johnson syndrome and toxic epidermal necrolysis (SJS/TEN) from CTLA-4 and PD-1/PD-L1 inhibitors are rare but they portend poor prognosis with mortality rates of 10% for SJS and 50% for TEN." (PMID 36938327, 2023).
tubular carcinomas (1 paper, 2018). "Groups III & IV, summary of the breast invasive lobular and tubular carcinomas showing the CTLA-4 staining reactions, scores, interpretations, and percentages of stained lymphocytes." (PMID 29672601, 2018).
uterine sarcomas (1 paper, 2022). "Together, these findings provide support for screening checkpoint proteins, such as PD1, PD-L1, IDO, and CTLA-4 in post-surgical uterine sarcomas as they provide the means for the utilization of targeted immunotherapies in these rare but aggressive uterine sarcomas." (PMID 36104728, 2022).
vascular tumors (1 paper, 2024). "Monoclonal antibodies (MABs) targeting CTLA-4, PD-1, and PD-L1 are currently ideal drugs for the treatment of solid and vascular tumors." (PMID 38979409, 2024).
viral myocarditis (1 paper, 2024). Myocarditis that is caused by an infection with a viral agent. "Consistent with the data obtained from viral myocarditis, we found that myocardial injury‐related genes including Timp1, AW112010, and Ctss were significantly increased by anti‐CTLA4 m2a antibody in the MZs of EAM mice." (PMID 38978328, 2024).
vulvar melanoma (1 paper, 2022). A usually pigmented, nodular or polypoid malignant neoplasm that originates from melanocytes and arises from the vulva. "In our cohort, two patients with vulvar melanoma received anti-PD1/PDL1 treatment and one patient with nasal melanoma received anti-CTLA4; none of them responded." (PMID 35159047, 2022).
ZIKV infection (1 paper, 2024). "Furthermore, the CD4+ TEMRA cells displayed higher proportions of cells co-expressing Ki-67 and the immune checkpoint markers CTLA-4 and PD1, at this early stage of the ZIKV infection." (PMID 38722858, 2024).